RN7SL430P (RNA, 7SL, cytoplasmic 430, pseudogene)
Gene: Miscellaneous RNA gene on chromosome 9 (112,272,596 to 112,272,837, reverse strand). Ensembl gene ENSG00000243911.
Homologues: Orthologues: chimpanzee Metazoa_SRP (100% identical), rabbit Metazoa_SRP (77% identical), macaque Metazoa_SRP (57% identical). Paralogues in human: RN7SL1 (82% identical), RN7SL2 (80% identical), RN7SL3 (80% identical), RN7SL451P (80% identical), RN7SL769P (80% identical), RN7SL45P (79% identical), RN7SL478P (78% identical), RN7SL88P (78% identical), Metazoa_SRP (77% identical), RN7SL627P (77% identical), RN7SL630P (77% identical), RN7SL251P (77% identical), and 708 more.